CRP (C-reactive protein)
Diseases named in the same sentence as CRP in open-access papers (continued):
Sharing a sentence is not in itself a finding about the gene and the disease.
infection (continued). "CRP is a protein synthesized by the liver in response to inflammatory cytokines during conditions such as inflammation, infection, and trauma." (PMID 40716028, 2025). "CRP is a marker of infection and inflammation, which increases in level during bacterial infections." (PMID 41458536, 2025). "Infection-related composite indices were also increased, with a CRP/albumin ratio of 8.70 ± 11.97, neutrophil-to-lymphocyte ratio 3.56 ± 3.06, and ESR × CRP 4228.14 ± 2246.19." (PMID 41300930, 2025). "Early responsiveness to marrow activation makes it especially valuable in the initial phase of infection, possibly before CRP or PCT elevation." (PMID 40723124, 2025). "Some studies have shown an increase in commonly used markers of infection, such as C-reactive protein (CRP) and white blood cell count (WBC), however, other results have refuted this." (PMID 40447994, 2025). "Elevated CRP levels correlate with the severity of the infection and provide information about the inflammation." (PMID 40003700, 2025). "Cross-tabulation demonstrated a significant correlation between raised CRP and early postoperative infection (χ2 = 10.73, p = 0.002)." (PMID 40861637, 2025). "One patient in this age group had a mixed infection involving both bacterial and viral respiratory pathogens, which resulted in critical SpO2 levels of 89% and a significantly elevated CRP level of 171.9 mg/L." (PMID 41210881, 2025). "In infants aged 7–11 months, a sharp increase in mean CRP levels was observed during bacterial mono-infection, with levels reaching 137.2 mg/L, which is ten times higher than the normal range of 0–5 mg/L." (PMID 41210881, 2025). "Elevated CRP levels are observed in response to infection, inflammatory conditions, trauma, and ageing." (PMID 41281897, 2025). "Procalcitonin (PCT) and C-reactive protein (CRP) are widely used biomarkers for detecting inflammation and infection in clinical settings." (PMID 40731765, 2025). "This interpretation aligns with the concept that a secondary rise or plateau in CRP after the initial postoperative peak can signal occult infection or surgical-site complication." (PMID 41153812, 2025). "These markers are used to assess infection status, disease severity, and prognosis (e.g., CRP > 92.4 mg/L predicts mortality with 91% sensitivity)." (PMID 40843250, 2025). "In emergency clinics and community-acquired infections, NLR is considered a simpler, faster, and more accurate biomarker for predicting infection compared to white blood cells and CRP." (PMID 41488886, 2025). "Reevaluation of infection markers revealed a progressive increase in C-reactive protein (CRP) and interleukin-6 (IL-6), along with a gradual decrease in platelet count (PLT)." (PMID 40547132, 2025). "Our study confirmed that acid-suppressing drugs can alter the microbial composition of peripancreatic effusions and increase markers of postoperative infection, such as C-reactive protein." (PMID 40860654, 2025). "Studies have shown that when CRP levels rise above 50 mg/L, there is a 90% probability that the infection is bacterial." (PMID 41210881, 2025). "Patients receiving ozone therapy demonstrate reductions in inflammatory markers (CRP, IL-6, D-dimer), improved redox balance, decreased infection frequency, and better overall immune performance." (PMID 41614780, 2025). "According to the regression analysis for the categoric data, the simultaneous detection of parainfluenza viruses with RSV brought a higher mean of CRP values (p 0.026 < 0.05) in comparison with a mono-infection with a parainfluenza virus." (PMID 40310049, 2025). "Blood test results revealed normalized leukocyte counts at 6.9 × 109/L, but indicated high levels of infection markers, including a C-reactive protein (CRP) concentration of 70 mg/L and a sedimentation rate (SR) of 33 mm/h." (PMID 40034189, 2025). "Another study compared CRP levels in serum of patients with odontogenic infections before and 7 days after elimination of the infection source." (PMID 41464835, 2025).
infection (continued). "The infection risk prediction decision tree was constructed using WBC pod3, CRP pod3, PLR pod3, PCT pod3, and other predictors from the training set." (PMID 41488886, 2025). "Over the past years, PCT, CRP and IL-6 have been commonly used as indicators of inflammation in clinical infections, their elevated values are usually considered to be associated with an exacerbation of the infection, but they have some limitations." (PMID 40046191, 2025). "The CRIME80 score focuses on elderly patients, identifying age, CRP, and infection characteristics as predictors of poor outcome." (PMID 41465792, 2025). "Multivariate models controlled for covariates such as age, sex, BMI, CRP, and a symptom‐based measure of cold‐like active infection." (PMID 39613339, 2025). "Infection control efficacy was evaluated using inflammatory biomarkers, including CRP levels, with normalization trends indicating resolution of systemic inflammation." (PMID 40703270, 2025). "The findings of this systematic review align with previous meta-analyses and clinical trials that have established CRP as a primary biomarker for detecting early post-surgical infections, particularly in abdominal and colorectal surgeries." (PMID 40342430, 2025). "Canakimumab, a monoclonal antibody targeting IL-1β, reduced cardiovascular events in patients with previous myocardial infarction and a CRP >2 mg/L, but increased infection-related deaths." (PMID 40796058, 2025). "Secondly, certain critical clinical data, including the infection site, procalcitonin level and CRP were excluded from the study owing to insufficient information in the database." (PMID 41341126, 2025). "C-reactive protein (CRP) is an acute-phase protein that is produced by the liver in response to inflammation and is widely used as a biomarker for systemic inflammation and infection." (PMID 40507811, 2025). "This systematic review highlights the diagnostic utility of CRP, PCT, and NLR in detecting early post-surgical infections, emphasizing their clinical relevance across various surgical specialties." (PMID 40342430, 2025). "In severe cases of infection or when CRP increased, broad-spectrum antibiotics were routinely used in over 70% of patients." (PMID 39860338, 2025). "At the molecular level, our data with different infection doses have revealed that CRP accomplishes the hepatic trapping of circulating bacteria through the complement-dependent and independent mechanisms." (PMID 41214213, 2025). "When CRP values are low or within the normal range, early infection should be considered, prompting timely imaging with high diagnostic capability, such as MRI, and early biopsy planning for definitive diagnosis." (PMID 40943760, 2025). "On the other hand, we also acknowledge recent prospective data that question how much early postoperative CRP alone can really single out impending infections in thoracic surgery." (PMID 41153812, 2025). "CRP is an acute-phase protein synthesized by the liver, increasing during inflammation, often used to assess inflammation and infection." (PMID 40440129, 2025). "Other researchers have demonstrated that elevated levels of specific inflammatory markers present during the acute phase of infection—namely, CRP, IL-6, and tumor necrosis factor (TNF)—are correlated with an increased risk of developing long COVID." (PMID 41302639, 2025). "The antibiotic decision-making tool included an infection prediction score (NeoHoP), and a point-of-care C-reactive protein test (CRP) performed at HAI diagnosis and 24 h later." (PMID 39838378, 2025). "Conventional biomarkers for the initial assessment of bacterial or viral (B/V) infections include white blood cells (WBCs), lymphocytes (LYMs), C-reactive protein (CRP) and procalcitonin (PCT)." (PMID 40843077, 2025). "In that setting—essentially an active infection being surgically managed—the CRP was uniformly high and thus less informative for predicting outcomes." (PMID 41153812, 2025).
infection (continued). "The mean admission CRP level of 23 patients who were considered as having an infection and administered antibiotic therapy was 12.79 mg/dL." (PMID 40125102, 2025). "Patients treated with monotherapy presented with milder infections, less fever and lower Charlson comorbidity scores, with significantly lower baseline C-reactive protein levels (102.6 versus 65.7 mg/L; P = 0.006)." (PMID 40995023, 2025). "In contrast, a twofold increase in this parameter was observed in proven viral mono-infections (mean CRP 22.8 ± 35.8 mg/L)." (PMID 41210881, 2025). "Systemic inflammatory markers such as C-reactive protein (CRP) and erythrocyte sedimentation rate (ESR) are frequently elevated in malignancy, yet they also respond to trauma and infection, limiting diagnostic precision." (PMID 41464189, 2025). "The effectiveness of the commonly utilized biomarkers C-Reactive Protein (CRP) and Procalcitonin, in aiding with the diagnosis of infection during MCS is fraught with limitations and remains under investigation." (PMID 40523137, 2025). "We observed a significant association of clinical signs of infection, higher stages of WIfI infection score, and higher levels of CRP values in a univariable analysis on LS." (PMID 40660298, 2025). "Synthesized primarily by hepatocytes in response to interleukin-6 and other pro-inflammatory cytokines, CRP levels can rise rapidly within hours of infection or tissue injury, often reaching peak concentrations within 48 h." (PMID 40647525, 2025). "CRP levels are normally low but increase significantly in the presence of acute or chronic inflammation, infection, trauma or certain serious diseases." (PMID 40141715, 2025). "According to the entry definitions we proposed, PMR with normal baseline ESR and CRP concentrations, post-infection PMR and PMR following vaccination (with the exception of rare and questionable ASIA syndromes) should be categorized as subsets of disease." (PMID 40508840, 2025). "Procalcitonin (PCT), white blood count (WBC), and C-reactive protein (CRP) are the most commonly used biomarkers for detecting infection." (PMID 41007066, 2025). "Elevated D-dimer levels have been linked to increased coagulation and potential microvascular injury, while higher procalcitonin and C-reactive protein, together with lower albumin levels, indicate systemic inflammation and possible infection." (PMID 41551652, 2025). "Signs of infection included chest retraction (19.9%), high levels of CRP (19.1%), and tachypnea (13.2%)." (PMID 39858390, 2025). "No significant impact was observed for heart rate, SpO2 ≤ 93%, CRP>8 mg/L, whole lung infection percentage, or highest lobe infection percentage." (PMID 40950976, 2025). "Inflammatory parameters such as CRP were found to be significantly increased in the CP group and even more so in the SP group, indicating a severe infection." (PMID 40236451, 2025). "CRP levels increased progressively in bacteremic cases (Day 1 median: 6.79 mg/dL → Day 2: 12.0 mg/dL), supporting its utility in monitoring infection trends during treatment." (PMID 40647525, 2025). "The low accuracy of the ROC curves for SOFA, lactate, and CRP in predicting infection or mortality suggests the need to identify new biomarkers." (PMID 40802437, 2025). "Levels of CRP and creatinine in the four AGMs that survived HeV-g2 infection returned to baseline by 21 DPI and remained there until the 35 DPI." (PMID 40768740, 2025). "CRP is characterized by early sensitivity to infection‐induced inflammation or tissue damage and rapid recovery as the lesion subsides and the tissue structure and function return." (PMID 39945309, 2025). "CRP, an acute-phase protein, is significantly upregulated in response to inflammation, tissue injury, or infection through cytokine-mediated pathways." (PMID 40801194, 2025).
infection (continued). "Infection parameters in the blood, including C-reactive protein (CRP), erythrocyte sedimentation rate (ESR), and total and differential leucocyte counts, were within normal limits." (PMID 40918794, 2025). "2.2.6.Acute phase reactants such as CRP and procalcitonin can aid in the diagnosis of infection and assessment of the response to therapy." (PMID 39961976, 2025). "Laboratory tests including complete blood count, urinalysis, and CRP levels can assist in identifying the source of infection." (PMID 41040639, 2025). "When evaluating laboratory parameters in the deep-seated infection group, CRP, sedimentation rate, fibrinogen, and D-dimer values are higher in cases of deep tissue invasion." (PMID 40868411, 2025). "It is also worth noting that CRP, used as marker for systemic inflammation, is not only affected by inflammation, but also by transient infections." (PMID 41294682, 2025). "During infection or trauma, CRP levels can rise rapidly, demonstrating high sensitivity in the early stages of infection." (PMID 40098935, 2025). "Nonetheless, impaired synthesis from liver injury can lead to falsely low CRP levels, potentially hiding the presence of infection even when it exists." (PMID 41007066, 2025). "A secondary elevation or failure of CRP to decrease has been suggested as an early indicator of infection in adult spinal surgery and arthroplasty." (PMID 41226908, 2025). "As a sensitive indicator of systemic inflammation, hs‐CRP elevation reflects an activated biological response to cardiac injury or infection, which under physiological conditions facilitates tissue repair and functional recovery." (PMID 41223074, 2025). "CRP levels have been reported to be elevated in over 90% of cases and a persistently elevated CRP is highly correlated with the presence of infection." (PMID 40251183, 2025). "For ankle fractures the mean peak CRP was around 34-39 mg/L and showed CRP as a predictor for infection in fracture surgery has showed a sensitivity 60–100%, specificity of 65–98.4%, negative predictive value 17% and positive predictive value 98%." (PMID 40156733, 2025). "Similar findings have been reported in other studies, where the decline of acute-phase proteins (e.g., C-reactive protein) coincided with the activation of antibody responses during infection resolution." (PMID 40284260, 2025). "CRP serves as a sensitive systemic inflammation marker that can increase up to 1,000-fold at infection or inflammation sites." (PMID 40611921, 2025). "C-reactive protein (CRP) is an acute time-phase reactive protein that is usually significantly elevated in conditions such as inflammation and infection." (PMID 40988175, 2025). "The postoperative courses of the mean CRP values were similar between those who remained reinfection-free and those who experienced a re-infection." (PMID 40565868, 2025). "CRP levels typically begin to rise within approximately 6 hours after the onset of infection or inflammation." (PMID 40638513, 2025). "In recent years, serum CD64, VEGF, SDF-1, NLR, and the CRP/ALB ratio have been increasingly recognized for their potential in early infection diagnosis." (PMID 41019129, 2025). "CRP, as the most common inflammatory marker, rises rapidly in response to inflammation or infection due to cellular damage that triggers the release of cytokines and interleukins, stimulating the liver to synthesize and release CRP." (PMID 40144928, 2025). "Of primary severe infection definition episodes, 51% had an RT-PCR nasal swab, at least one of white blood cell count, neutrophil count, CRP or PCT, and a blood culture completed." (PMID 40661255, 2025). "Studies in orthopaedic and cardiothoracic settings showed elevated postoperative PCT levels (≥0.5 ng/mL) strongly correlated with confirmed infections, outperforming CRP and WBC in sensitivity and specificity (80-100%)." (PMID 40995285, 2025).
infection (continued). "The suggested cutoff values can prevent unnecessary delays in chemotherapy cycles by eliminating false considerations of infection in patients with high CRP levels." (PMID 40125102, 2025). "This increase in CRP levels in response to SA likely reflects the acute-phase response initiated by the host's immune system to infection." (PMID 41163924, 2025). "To establish a CRP KO mouse model of infection with S. pneumoniae type 3, strain WU2, we titrated the dose of bacteria needed for inoculation." (PMID 40740789, 2025). "When infection occurs in patients with diabetes-related foot ulcers, plasma levels of CRP rise rapidly and dramatically, up to 1,000 times higher than normal." (PMID 40373091, 2025). "CRP increases rapidly as part of a number of inflammatory diseases and plays important roles by protecting against infection, clearance of damaged tissue, prevention of autoimmunization, and regulation of the inflammatory response." (PMID 41301983, 2025). "Patients with clinically diagnosed infections exhibited more prolonged CRP elevation, often >100 mg/L beyond POD4, whereas uncomplicated cases declined after the POD2 peak; these trends did not achieve statistical significance in this cohort." (PMID 41153812, 2025). "C-reactive protein (CRP), an acute-phase reactant produced by the liver, is rapidly synthesized in response to infection and inflammation." (PMID 40723359, 2025). "To systematically evaluate the diagnostic accuracy of CRP, PCT, and WBC in detecting early post-surgical infections, we structured this systematic review based on the PICO (Population, Intervention, Comparison, and Outcome) framework." (PMID 40342430, 2025). "Another nuance is that CRP can be elevated for many reasons besides infection, including the normal tissue injury of surgery, inflammatory conditions, or minor complications that do not progress." (PMID 41153812, 2025). "Elevated inflammatory markers, including CRP and IL-6, were also observed, reflecting infection-related responses." (PMID 41210029, 2025). "CRP is a sensitive marker reflecting inflammation and infection in the body, with lower CRP levels generally indicating better inflammation control and prognosis." (PMID 40230802, 2025). "CRP levels reflect infarct size, systemic immune activation, and infection status, all of which influence prognosis." (PMID 40869247, 2025). "Neutrophil (79.22 ± 13.86), White Blood Cell (WBC) (14.05 ± 11.14), CRP (145.76 ± 125.91) and procalcitonin (3.35 ± 5.29) levels were well above the average when immune function tests and infection panel values of intensive care unit patients were analyzed." (PMID 41041442, 2025). "In clinical trials, CRP is commonly used to monitor the inflammatory process and the severity of infections." (PMID 40427060, 2025). "Incorporating routine CRP trends can effectively support antibiotic stewardship, aid in distinguishing infection depth and facilitate safe, timely discharge planning in hand surgery patients." (PMID 41556000, 2025). "Healthy individuals have low levels of serum CRP, which usually increases in various inflammation, infection, stress, trauma, surgery, and tissue injury." (PMID 40313464, 2025). "CRP trends, when combined with a clinical assessment, help monitor infection progression or treatment response for critically ill patients." (PMID 39941194, 2025). "Adding CRP ≥ 2 mg/dL improved predictions for infection (AUC: 0.909) and LOS ≥ 7 days (AUC: 0.798), outperforming the C-ACS score (AUC: 0.807) and SHR (AUC: 0.784)." (PMID 40460177, 2025). "Previous studies have explored several risk factors for infection after PLIF, such as hemoglobin, white blood cell count, diabetes, surgery duration, age, BMI, serum amyloid A, C-reactive protein, and lymphocytes." (PMID 41488886, 2025).